IL25 (interleukin 25)
Diseases named in the same sentence as IL25 in open-access papers (continued):
Sharing a sentence is not in itself a finding about the gene and the disease.
helminth infection (continued). "Parasitic helminth infection or systemic IL-25 administration can induce a subset of migratory ILC2s that preferentially express the IL-25 receptor but not ST2." (PMID 35757747, 2022). "We perceive that the IL-25/ILC2/Th2 axis is responsible for the positive effect of the Th2 response in helminth infection related diseases." (PMID 36119076, 2022). "IL-25 is released from intestinal tuft cells stimulated by helminth infection, and acts on ILC2 cells to release type 2 cytokines, including IL-5 and IL-1343." (PMID 35288645, 2022). "When triggered by helminth infection, tuft cells secrete interleukin-25 (IL-25) basolaterally and subsequently evoke an immune response." (PMID 32477197, 2020). "This IL-25-responsive NBNT population was later observed in the context of helminth infection where it was described as a prominent producer of type-2 cytokines during infection." (PMID 32793230, 2020). "Tissue remodeling that mimics the histological features of a helminth infection, reinforcing the importance of IL-25 signaling in type 2 immunity." (PMID 32849506, 2020). "IL-25 is mainly produced by tuft cells, recently recognized as crucial initiators of the mucosal type 2 immunity during helminthic infection." (PMID 33371444, 2020). "In these studies, administration of the S1P-receptor agonist FTY720 prevented the appearance of iILC2s in the lung after IL-25 administration or helminth infection, indicating the requirement for iILC2s to egress from lymphoid organs into circulation." (PMID 32793230, 2020). "While recent studies have uncovered the origin and the mechanisms of action of IL-25, several doubts remain concerning the role of IL-25 in the generation of protective Th2 responses to intestinal helminth infections." (PMID 33276813, 2020). "In particular, IL-25, which, in the intestine, is uniquely secreted by tuft cells, is a key signalling molecule secreted in responses to helminth infections." (PMID 32477197, 2020). "In an environment of helminth infection, IL-25 acts as a mediator of the activation of ILC2s promoting the polarization of the immune response towards a Th2 phenotype." (PMID 33276813, 2020). "Within the small intestine, tuft cell-derived IL-25 is required for the “weep and sweep” response that rids the host of helminth infection." (PMID 32116793, 2020). "In the small intestine they have been described to produce interleukin (IL)‐25 upon helminth infection." (PMID 31107965, 2019). "In response to helminth infection, innate immune cells and intestinal epithelial cells secrete Th2 cytokines including IL-4, IL-5, IL-9, IL-13, IL-25, IL-33 and thymic stromal lymphopoietin (TSLP)." (PMID 30670631, 2019). "Initial reports of ILC2s established that their expansion during helminth infection is driven largely by IL-17 family member IL-25 (IL-17E)." (PMID 31072011, 2019). "Studies have indicated that intestinal epithelial tuft cells produce IL-25 after helminth infection." (PMID 31296243, 2019). "IL-33 responsive ILC2s present in the steady state are called natural ILC2s (nILC2), whereas IL-25 responsive ILC2s elicited upon exposure to IL-25 or helminth infection are referred to as inflammatory ILC2s (iILC2)." (PMID 31134050, 2019). "Firstly, the expansion of eosinophil and alternatively activated macrophage numbers seen following helminth infection is strongly amplified by IL-25." (PMID 30238872, 2018). "During helminth infection, IL-25 secreted by tuft cells activates type 2 ILCs to produce IL-13, which induces the differentiation of increased numbers of tuft and goblet cells from epithelial progenitor cells." (PMID 29922293, 2018). "In models of helminth infection, production of IL-25 by intestinal epithelial tuft cells regulated the helminth-induced type 2 immune response and facilitated worm expulsion." (PMID 29922293, 2018).
helminth infection (continued). "In helminth infections, type 2 immunity is initiated at the site of invasion by epithelial cells, which release the alarmins IL-25 and IL-33, inducing innate lymphoid cells (ILCs) to produce IL-13 and other cytokines." (PMID 28302598, 2017). "Through its ability to induce IgE production and eosinophilia, IL-25 plays an essential role in host defense to helminth infections." (PMID 27165713, 2016). "Consistent with this, when IL-25−/− mice were used in another model of helminth infection, Nippostrongylus brasiliensis, the protective role of IL-25 was dependent on its ability to induce type-2 cytokine production." (PMID 27165713, 2016). "IL-25 is known to have a protective role against helminth infections through the induction of a Th2 response." (PMID 27089535, 2016). "In summary, although the role of tuft cells and IL-25 in the outcome of intestinal helminth infections has been scarcely studied, our results indicate that they play a role in host resistance or susceptibility to infection." (PMID 27658962, 2016). "They expand strongly in vivo in response to IL-25 and IL-33, and represent the predominant early source of IL-5 and IL-13 during allergic inflammation and worm infection." (PMID 25659095, 2015). "IECs are thought to represent the major source of early IL-25 and IL-33 following helminth infection." (PMID 23935505, 2013). "During helminth infection, intestinal epithelial cells induce the production of IL-25, IL-33, and TSLP." (PMID 23653627, 2013). "In addition, following intestinal helminth infection, IL-25 regulated type 2 cytokines to alleviate chronic inflammation in the gastrointestinal tract." (PMID 37005677, 2023). "Because IL-25 signaling contributes to the upregulation of the intestinal adiponectin during T. spiralis infection, the intestinal epithelial cells were isolated from Il17rb−/− mice and evaluated for the adiponectin expression during helminth infection." (PMID 37635188, 2023). "In addition to helminth infection, IL-25 induces inflammatory ILC2s in the small intestines to proliferate and traffic to the lymphatics and blood circulation." (PMID 36941691, 2023). "The alarmins IL-33, IL-25 and TSLP are mainly secreted by stromal and epithelial cells in tissues and were linked to chronic inflammatory diseases, such as allergic lung inflammation, or to resistance against worm infections." (PMID 37063913, 2023). "It is widely thought that IL-25 is an ‘alarmin’ for the helminth infection." (PMID 36119076, 2022). "Moreover, iILC2 migrate from the intestinal lamina propria to other organs, including lung and liver, dependent on chemotaxis mediated by sphingosine 1-phosphate after injection of IL-25 or helminth infection." (PMID 35707544, 2022). "It was long appreciated that IL-25 is one of the earliest cytokines induced in response to helminth infection, but the cells that sense helminths and produce IL-25 were unknown until the simultaneous discovery that tuft cells were the elusive source." (PMID 35271673, 2022). "These KLRG1+CD90lo ILC2 may be similar to the inflammatory ILC2 that have been reported to proliferate in the small intestine, then migrate to the lung and other tissues in response to helminth infection or IL-25 treatment." (PMID 35534698, 2022). "Both ILC2s and macrophages expressed the MIF receptor CXCR4, indicating that MIF may act as an essential co-factor on both cell types to activate responses to IL-25 in helminth infection." (PMID 35288645, 2022). "First of all, IL-25 is crucial for the clearance of helminth infections." (PMID 36119076, 2022). "Apart from their temporal origin, ILC2s exhibit a tissue-dependent responsiveness to IL-33 and IL-25, with IL-33-responding ILC2s residing mainly in the lung and adipose tissue in steady-state conditions and IL-25-responding ILC2s mainly found in the intestine upon helminth infection." (PMID 36305904, 2022).
helminth infection (continued). "Moreover, IL-25 deficient mice have significantly reduced ILC2s in the SI at steady state and after worm infection, suggesting a critical role of IL-25 in maintenance and activation of intestinal ILC2s." (PMID 33968080, 2021). "Indeed, in systemic and epithelium-specific Il-25 knockout mice helminth infections were only inefficiently cleared." (PMID 33869257, 2021). "Furthermore, Tuft cell numbers increase during helminth infections, in turn secreting more IL-25 to promote a more efficient activation of ILC2s during the defense response against these pathogens." (PMID 34759931, 2021). "This is because a recent study reported that a population of inflammatory ILC2s (iILC2s), which are circulating cells and derived from intestinal ILC2s, could migrate to the lung after IL-25 stimulation or helminth infection." (PMID 32431711, 2020). "The importance of IL-33 and IL-25 during helminth infection is suggested by the higher susceptibility of mice lacking these alarmins." (PMID 33371444, 2020). "As deficiency in either IL-25 or IL-33 results in greatly enhanced susceptibility to helminth infection, these alarmins are not generally redundant." (PMID 31024526, 2019). "Interestingly, three independent groups recently demonstrated that intestinal epithelial cells, specifically rare, chemosensory Tuft cells, expand during worm infection and are necessary producers of IL-25." (PMID 31072011, 2019). "As IL-25 promotes the accumulation of multipotent progenitor cells in naïve mice, it seems that there is a positive-feedback mechanism to amplify Th2 immunity during helminth infection." (PMID 23653627, 2013). "In another mucosal context, the intestine, IL-25 has been described to play a role in the protection against helminth infection by inducing a strong type-2 innate inflammation which is dependent upon the activation of IL-17BR+ nuocytes and their production of IL-13." (PMID 22539101, 2012). "Because IL-25 expression in the intestinal tissue of T. spiralis-infected mice was most strongly associated with the level of adiponectin, we tested the possibility that IL-25 signaling in the intestine induced by helminth infection might regulate adiponectin expression." (PMID 37635188, 2023). "Therefore, the biological function of IL-25 in the helminth infection is intriguing." (PMID 36119076, 2022). "However, there has been no direct evidence to verify that helminth infection-induced IL-25 is associated with tumorigenesis, which is a promising area that deserves us to explore in depth in the future." (PMID 36119076, 2022). "This hypothesis was recently confirmed by Huang and colleagues who reported that iILC2s expanded in the small intestine in response to helminth infection or exogenous IL-25 delivered intraperitoneally, but that intranasal administration of exogenous IL-25 did not induce iILC2s in the lungs." (PMID 31019505, 2019). "The cytokines IL-25 and IL-33 (a member of the IL-1 family) have been shown to play a crucial role in the regulation of type 2 cytokine production, to be produced rapidly following helminth infection, and to promote protective immunity against Trichuris muris, Nippostrongylus brasilienis and Hp." (PMID 23935505, 2013). "We show that epithelial Elp3, a tRNA-modifying enzyme, promotes tuft cell differentiation and is consequently critical for IL-25 production, ILC2 activation, goblet cell expansion and control of Nippostrongylus brasiliensis helminth infection in mice." (PMID 39085648, 2024). "Damaged IECs release cytokines such as IL-33, IL-25, and thymic stromal lymphopoietin (TSLP), playing a crucial role in worm infections." (PMID 38203591, 2023). "In intestinal helminth infection, tissue-resident group 2 innate lymphoid cells (ILC2) modulated mucosal barrier homeostasis by responding to tuft cell–derived IL-25." (PMID 37005677, 2023).
helminth infection (continued). "These include IL-33, IL-25 and TSLP, a prototypical group of cytokines produced in response to specific stimuli such as tissue damage by allergen exposure, and helminth infection, which induce type 2 immune responses." (PMID 34759931, 2021). "Ultimately, mice with ineffective mast cells are unable to prime an effective type 2 immune response regulated by IL-33, IL-25 and TSLP in response to helminth infection and are unable to clear the parasites." (PMID 32363166, 2020). "This correlation between reductions in these epithelial derived cytokines and the delayed Th2 response seen experimentally is further evidence in support of the Th2 polarizing effect of IL-25, IL-33 and TSLP in certain helminthic infections." (PMID 30670631, 2019). "Mast cells are required for the production of IL-25, IL-33, and TSLP by intestinal epithelial cells following helminth infection and during subsequent anti-helminth responses." (PMID 23653627, 2013). "ILC2s migrate from the intestine to the lung in response to IL-25 and helminth infections, but this phenomenon has not been observed in adipose tissue." (PMID 35784368, 2022). "Inhibition of mast cell function in vivo has also been linked to an overall reduction in IL-33, as well as IL-25 and TSLP both in the context of helminth infection as well as without." (PMID 32363166, 2020). "An important point of consideration is that ILC2s are not the sole target of IL-25 activation in helminth infection, given evidence that other innate cell types such as monocytes, other myeloid cells and NKT cells are responsive to this cytokine." (PMID 31024526, 2019). "In the absence of either IL-25 or IL-33, resistance to helminth infections is severely impaired, as is the case in IL-4Rα or STAT6 deficiency." (PMID 28302598, 2017). "The cytokines, IL-25, IL-33, and thymic stromal lymphopoietin (TSLP) assume key roles here and in mice, precursors of lineage negative (ILC2) that can respond to IL-25/33 and helminth infection are found in many tissues around the body 61,68." (PMID 24942690, 2014). "Overall, these results are of particular significance as they suggest that IL-25 and IL-33 may play nonredundant roles in helminth infection and discrete pathways may be needed for host immune responses to different intestinal helminth parasite infections." (PMID 28898280, 2017). "Indeed, studies in mice show that ILC2 activation in response to helminth infection or A. alternata exposure is only completely abolished in combined absence of IL-25 and IL-33 signaling." (PMID 26965110, 2016). "Our data suggest that IL-25 is essential for type-2 cytokine production by mesenteric lymph node (MLN) cells, as well as being essential for IL-13 production by leukocytes in the intestinal mucosa; this result supports previous findings in helminth infection and in lung inflammation." (PMID 22539101, 2012). "In the rotavirus setting, tuft cells also became directly infected but showed no numerical expansion, and, in contrast to events during helminth infection, down-regulated IL-25 and leukotriene production, indicating a conventional type 1 antiviral state may be induced." (PMID 37887321, 2023). "However, IL-25 is expressed by intestinal epithelial cells, endothelial cells, type 2 CD4+ (Th2) cells, natural killer T cells (NKT), FcεR1-ligated mast cells, and eosinophils, and thus could come from a variety of cell types during helminth infection." (PMID 31072011, 2019). "While more sub‐cellular examination of IL‐25's activity is ongoing, IL‐33 and TSLP research has been hampered by a lack of clarity regarding their functional sources during helminth infections." (PMID 40944312, 2025). "To our knowledge, IL25 and IL21 polymorphisms in the Th17 pathway have not been previously associated with worm burden but we have recently hypothesized that they might play a role in worm infection response as they are Th17 pathway genes within SM1 and SM2 loci." (PMID 38033168, 2023).
helminth infection (continued). "Its level of direct interaction with TH2 cells during helminth infection is not clear, but considering ILC2 release of Areg is a topic of present interest, indirect signalling of TH2 cells via IL‐25 suggests itself as an interesting mechanistic axis in type two immunity." (PMID 40944312, 2025).
eosinophilia (45 papers, 2012 to 2025). "IL-25 induces eosinophil infiltration in the gut, which is potentially relevant in amebiasis as eosinophilia was also associated with reduced size and number of amebic liver abscesses in the gerbil model." (PMID 28246365, 2017). "Over-expression of IL-25 is associated with increasing eosinophilia and a TH2 dominant immune response." (PMID 28771607, 2017). "The effects induced by IL-25 seem to be very similar to those induced by IL-33, in that administration of both cytokines causes eosinophilia, splenomegaly, IgE secretion, production of other TH2-type cytokines, goblet hyperplasia and mucus production." (PMID 22360486, 2012). "IL-25, also known as IL-17E, is produced primarily by epithelial cells and enhances Th2-type immune responses, promoting eosinophilia, IgE production, and mucus secretion." (PMID 40981017, 2025). "Mice with transgenic expression of IL-25 exhibit eosinophilia and elevated levels of IgE, IgG1, IL-5, and IL-13." (PMID 39962262, 2025). "IL-17E (also known as IL-25) is structurally more divergent and functions through IL-17RA/IL-17RB to promote type-2 immune responses, including eosinophilia and allergic inflammation." (PMID 41226970, 2025). "Blockade of IL-17RB by SM17 is expected to interfere with IL-25 signaling, subsequently reducing the Th2-mediated inflammatory response, such as a reduction in cytokine release and eosinophilia in patients." (PMID 39717777, 2024). "TSLP, IL-5, IL-13 and IL-25 are the major proinflammatory cytokines that mediate eosinophilia-dominated type-2 inflammation." (PMID 37377967, 2023). "Of note, Il25 expression was decreased in neutrophilia-dominant mice when compared with control mice or eosinophilia-dominant mice." (PMID 37898756, 2023). "IL-25 protected through induction of eosinophilia as observed depletion of eosinophils by neutralizing antibody abrogated protection." (PMID 34400793, 2022). "This protection is thought to be conferred by IL-25-mediated eosinophilia since depletion of eosinophilia with anti-SiglecF administration abrogated the protection." (PMID 33502317, 2021). "IL-25 is known to increase eosinophils in the gut, and IL-25-induced eosinophilia protects against pathogenesis in Clostridium difficile colitis." (PMID 28246365, 2017). "These authors found that the increased expression of IL-25 they observed in nasal polyp tissues of patients with CRSwNP correlated with worse computerized tomography scores and blood eosinophilia." (PMID 28127565, 2016). "In vitro studies have shown that MDC and TARC, high-affinity CCR4 ligands, induce the selective migration of Th2 cells and IL-25-mediated Th2 responses in eosinophilia." (PMID 24658532, 2014). "More importantly, inducing this population by administration of IL-25 was sufficient for worm clearance and restored eosinophilia." (PMID 22360486, 2012). "IL-25 promotes the production of cytokines, IgE, and eosinophilia." (PMID 40800128, 2025). "Immune factors leading to eosinophilia, including the constitutive production of IL-25/IL-33/TSLP by epigenetically modified airway epithelial cells may be less influenced by ETI and may remain constant." (PMID 37525180, 2023). "The expression of Il25 is increased in eosinophilia-dominant mice compared with control mice." (PMID 37898756, 2023). "Compared to RV-A (RV-1B) infection, RV-C (RV-C15) infection induced higher BALF eosinophilia, mRNA expression of IL-5, IL-13, IL-25, Muc5ac and Gob5/Clca, protein production of IL-5, IL-13, IL-25, IL-33 and TSLP, and expansion of ILC2 in naive and HDM-immunized BALB/c mice." (PMID 35386658, 2022). "Currently, several biomarkers of TH2-mediated type 2 inflammation have been demonstrated including blood eosinophilia, fractional exhaled nitric oxide, and blood levels of IL-25 and blood periostin, all of which have been shown to correlate well with airway eosinophilia." (PMID 30736433, 2019).